IFNG (interferon gamma)
Diseases named in the same sentence as IFNG in open-access papers (continued):
Sharing a sentence is not in itself a finding about the gene and the disease.
HCMV infection (61 papers, 2007 to 2026). "During early cytomegalovirus infection, IFNγ is predominantly produced by ILC1s within the infected tissue and this precedes the activation of NK cells." (PMID 38567059, 2023). "In seven primary HCMV infections in D+R− kidney transplant patients we measured IFNγ responses from as early as 4 weeks after infection to mixes of HCMV proteins containing IE1 and IE2, latency-associated proteins (UL138, US28, LUNA and vIL-10), pp71 and US3." (PMID 36558866, 2022). "To begin testing this assumption, we characterized the development of IFNγ T cell responses following primary HCMV infection." (PMID 32670891, 2020). "In patients with active HCMV infection i.e. group 1 and group 2, mean concentrations of IFNγ, IL10 and IL8 were found to be quite similar." (PMID 32985571, 2020). "Pertinent to this study, it has been shown in the context of HCMV infection that Th1 type gB specific CD4+ T cells that secrete IFNγ and TNFα have also been shown to be able to mediate MHC class II restricted cytotoxicity." (PMID 24130479, 2013). "The response to pp65, especially IFNγ production, may serve as a key marker for identifying patients capable of controlling HCMV infection." (PMID 41599037, 2026). "During cytomegalovirus infection, NK cells acquire a memory phenotype exhibiting a recall response resulting in expansion upon re-encounter with antigen and secretion of high levels of IFNγ." (PMID 38567059, 2023). "In this study we have examined by FluoroSpot the IFNγ response to overlapping peptides from a much broader range of immunodominant HCMV proteins in D+R– kidney transplant recipients experiencing primary HCMV infection, correlated with patient DNAemia over a time course post-transplantation." (PMID 32670891, 2020). "Transcriptomic analysis revealed that HCMV infection dampened the regulatory pathways of interferon gamma (IFN-γ), tumor necrosis factor alpha (TNF-α), and interleukin-1 (IL-1), consequently abrogating the immune responses to M. massiliense coinfection in macrophages." (PMID 33013921, 2020). "Notably, ZNF683 is necessary for IFNγ production after human cytomegalovirus infection." (PMID 35458449, 2022). "The aims of this study were to determine whether HCMV-specific CD4+ T cells secreting cIL-10 increase with age and long-term viral carriage and to determine whether there are changes in breadth and frequency of the IFNγ-secreting T cell response to HCMV infection in healthy older donors." (PMID 28694811, 2017). "To investigate the immunomodulatory effects of treatment with Tα1 + PCDs in CD4+ and CD8+ T cells during HCMV infection, we evaluated the expression of CD2 and CD40L, as well as the production of TNFα, IFNγ and IL-2 using multiparametric cytometry." (PMID 38396631, 2024). "Analysis of multi-functional T-cell responses by intracellular staining for both human IFNγ and human TNFα indicates that HCMV-infected huBLT mice generate poly-functional T-cells in response to HCMV infection." (PMID 28428537, 2017). "Following expression under conditions mimicking the situation during hCMV infection, IE1 elicited a host transcriptional response dominated by the up-regulation of genes normally induced by IFNγ." (PMID 27387064, 2016). "Other studies have shown that even in the presence of IFNγ or IFNα or IFNβ neutralizing antibodies, HCMV infection can still be controlled by lymphocytes in a non-cytotoxic manner, with granzymes implicated in control." (PMID 32670891, 2020). "HCMV infection drives the expansion of a CD56dimCD57+NKG2C+ subset of NK cells, which display a highly differentiated phenotype, including reduced responsiveness to exogenous cytokine stimulation and epigenetic changes at the IFNG locus." (PMID 25855356, 2015).
HCMV infection (continued). "Conversely, NLV-T cells from LF donors secreted higher levels of cytokines IFNγ and TNF, and were more effective at eliminating HCMV-infected cells that had suppressed HLA expression, highlighting a potential advantage of the this cell population in responding to HCMV infection." (PMID 41494240, 2026). "Here, similar to IFNγ production, the degranulation of CD56dim NK cells increased in response to the LFL peptide only in samples of hCMVhigh donors, which additionally supports the notion that NK cell pre-experience with hCMV infection is needed to perform peptide-specific degranulation." (PMID 38534374, 2024). "Our view that measurement of IFNγ is not a robust biomarker is supported by two pieces of evidence: firstly, a clear lack of correlation between CD3+ T cell IFNγ responses and DNAemia resolution in a small cohort of D+R– kidney transplant patients undergoing primary HCMV infection was observed." (PMID 32670891, 2020).
brucellosis (60 papers, 2008 to 2026). Brucellosis is a bacterial infection that spreads from animals to people via unpasteurized dairy products or by exposure to contaminated animal products or infected animals. "Here the interferon-gamma gene expression over-expression induced by RB51 is a correlated profile of immune protection against brucellosis, which is caused by Brucella." (PMID 40777277, 2025). "According to the results, C allele, particularly at position -611 within IFNγ R1 gene promoter was related to a high risk of disease and can be considered as a risk factor for the susceptibility to brucellosis." (PMID 31582997, 2019). "One polymorphism in the promoter region of IFNγ R1 was located at position -611 and another one at position -56 in brucellosis patients compared to controls." (PMID 31582997, 2019). "The presence of C allele in position -611 in IFNγ R1 gene promoter was related to a higher risk of disease and susceptibility to brucellosis." (PMID 31582997, 2019). "NK cells also play a significant role in the pathogenesis of brucellosis through early production of IFNγ and their cytotoxicity, which is suppressed during the acute phase of the disease." (PMID 40996975, 2025). "Consistently, these genes associated with ‘interferon‐gamma response’ (e.g., IFNG, IRF1, SOCS1) are also enriched in brucellosis patients." (PMID 39135683, 2024). "It is well-known that Th1 immune responses and the production of interferon gamma (IFN-γ) are crucial for the control of brucellosis." (PMID 35888979, 2022). "IFNγ is understood to be the key effector in control of brucellosis in both the murine model and target species." (PMID 20637091, 2010). "Several studies have shown that interferon-gamma serum concentration may be recognized as an essential factor in chronic brucellosis." (PMID 34335092, 2021). "LncRNA IFNG-AS1 enhanced the expression of IFNγ in the immune response of brucellosis patients." (PMID 34222462, 2021). "Both IL12 and IFNγ are considered essential for protection against brucellosis." (PMID 19126207, 2009). "In line with this, the enrichment of genes linked to the ‘interferon‐gamma response’ pathway (e.g., STAT1, IFNG, IRF1, B2M, GAPDH) was also consistently observed in brucellosis patients." (PMID 39135683, 2024). "In vivo, IL-6, TNF-α, and CD80/CD86 are required for activation of the interferon gamma-producing CD4+ Th1 and CD8+ cytotoxic T cells, a protective response induced by the host against brucellosis." (PMID 34992597, 2021). "In vivo, IL-6, TNF-α, and CD80/CD86 are required in the activation of the interferon gamma-producing T CD4+ helper type 1 (Th1) and T CD8+ cytotoxic, a protective response induced by the host against brucellosis." (PMID 32765455, 2020). "One of these factors is interferon-gamma (IFN-), which is vital in the defense mechanism against infectious diseases such as brucellosis." (PMID 31582997, 2019). "Chronic brucellosis patients displaya defective Th1 response to PHA characterized by low-proliferation response ofCD4+ T-lymphocytes, diminished production of IL-2 and IFNγ, and low frequency of CD4+/CD25+ T-cellscompared to acute brucellosis patients." (PMID 19190764, 2008). "Multiple activation markers, such as CD69, MKI67, CCL5, CTLA4, IFNG and GZMB, were found to be enriched in the NK cells of brucellosis patients, indicating the presence of an activated NK cell response as a distinctive feature for brucellosis patients, especially for those at the acute stage." (PMID 39135683, 2024). "Same as subunit vaccines, DNA-based brucellosis vaccines can stimulate both humoral and cellular immune system arms, TCD4 and TCD8 helper cells, as well as a significant increase in IFNγ, TNF-α, and IL-12 levels, which IFNγ exerts a protective effect by boosting macrophage activity." (PMID 35923818, 2022).
endothelial dysfunction (60 papers, 2007 to 2025). In vascular diseases, endothelial dysfunction is a systemic pathological state of the endothelium (the inner lining of blood vessels) and can be broadly defined as an imbalance between vasodilating and vasoconstricting substances produced by (or acting on) the endothelium. "Multiple systemic vascular inflammatory disorders are associated with endothelial dysfunction and elevated levels of TNFα and IFNγ." (PMID 40894883, 2025). "The most important finding of the current study is that the endothelial connexin expression is not affected in any significant way by variations in the levels of factors which have been implicated in endothelial dysfunction, except for IFNγ." (PMID 38558785, 2024). "IFNγ then possibly induces insulin insensitivity seen as higher insulin to be an early marker of endothelial dysfunction and increased susceptibility to CVD later in life." (PMID 30138332, 2018). "Of the factors implicated in endothelial dysfunction and microvascular regulation, the most pronounced findings were that 1) Cx40 is induced by IFNγ, 2) the induction of Cx40 by IFNγ is mediated via the JAK/STAT pathway, and 3) this possibly affects the EC barrier function." (PMID 38558785, 2024). "IL-18 is a pro-inflammatory cytokine that is predominantly produced by macrophages and binds to its receptor on the membranes of endothelial cells, lymphocytes, and smooth muscle cells to cause the production of interferon gamma, endothelial dysfunction, and plaque instability." (PMID 35997998, 2023). "These infiltrating lymphocytes release various pro-inflammatory cytokines (e.g., tumor necrosis factor-alpha and interferon-gamma), which promote endothelial dysfunction and vascular remodeling." (PMID 39768778, 2024). "In contrast, preeclampsia is characterized by a predominance of Th1 T-cells and pro-inflammatory cytokines such as tumor necrosis factor (TNF) and interferon-gamma, which likely contributes to abnormal placentation and subsequent endothelial dysfunction." (PMID 35925932, 2022). "Cytokines, including TGF-β1, TNFα, IFNγ, IL-1β, and IL-17A, may regulate blood pressure through effects on endothelial dysfunction, salt and water balance, and sympathetic regulation." (PMID 31572188, 2019). "Moreover, the Cx37, Cx40, and Cx43 expression in endothelial cells is stable and, apart from IFNγ, not affected by a number of factors implicated in endothelial dysfunction and vascular diseases." (PMID 38558785, 2024). "In endothelial dysfunction, activation of the nuclear factor-kappa B (NF-κB) pathway has highlighted elevated levels of pro-inflammatory cytokines such as tumor necrosis factor-alpha, interleukin-1beta (IL-1 β), interleukin-6 (IL-6), and interferon gamma (IFN-γ)." (PMID 33467601, 2021). "Among the T cells involved, T helper 1 (Th1) cells play a pivotal role by secreting pro-inflammatory cytokines such as interferon-gamma (IFN-γ), which exacerbate endothelial dysfunction and promote macrophage activation." (PMID 40332077, 2025). "This process activates these immune cells and induces the release of additional pro-inflammatory cytokines, i.e., IL1α, IL1β, TNFα, IFNγ, and IL17, which may exacerbate endothelial dysfunction and contribute to the degradation of the endothelial glycocalyx." (PMID 39596318, 2024). "Endothelial dysfunction induces the secretion of coagulation factors (VWF and TM) the expression of cell adhesion molecules (ICAM, VCAM) and pro-inflammatory cytokines (TNFa, IFNγ, etc.), while it also activates the complement system." (PMID 36765638, 2023). "M1 macrophages, induced by stimuli such as interferon-gamma (IFN-γ) and lipopolysaccharide (LPS), secrete pro-inflammatory cytokines (TNF-α, IL-1β, IL-6) and reactive oxygen species (ROS), thereby amplifying vascular inflammation and contributing to endothelial dysfunction and plaque instability." (PMID 40871049, 2025).
Alzheimer disease (59 papers, 2006 to 2026). A progressive, neurodegenerative disease characterized by loss of function and death of nerve cells in several areas of the brain leading to loss of cognitive function such as memory and language. "Alzheimer: Higher levels of C-C motif chemokine 20 and interferon gamma were associated with an increased risk of Alzheimer's disease (AD), while higher levels of monocyte chemoattractant protein-1 and C-X-C motif chemokine 9 were linked to a reduced risk of AD." (PMID 41399369, 2026). "Notably, IFNγ, a potent regulatory cytokine, has been implicated in activating microglia and promoting brain inflammation in Alzheimer’s disease." (PMID 37569663, 2023). "Indeed, the inhibition of iP activity was associated with decreased IFNγ-dependent expression of pro-inflammatory cytokines in microglia and attenuation of disease progression in murine models of Alzheimer’s disease and experimental encephalomyelitis." (PMID 34063751, 2021). "A GO/KEGG analysis indicated that the related gene sets in these cells were enriched including “Cellular response to interferon-gamma”, “Cytokine cytokine receptor interaction”, “Alzheimer’s disease”, and “Parkinson’s disease”." (PMID 37121980, 2023). "BLNK assists in activation of immune cells, APOE codes for apolipoprotein associated with Alzheimer’s disease and IRF1 is activated by interferon gamma and regulates expression of antiviral genes." (PMID 34681730, 2021). "Nevertheless, due to their involvement in Alzheimer’s disease pathophysiology, it would be worth further studying the implications of their downregulation in response to LPS and LPS + IFNγ." (PMID 30382133, 2018). "Alternatively, C4d might be directly activated by other factors such as neoplasias, neurodegeneration like Alzheimer’s disease, or induced in astrocytes by activation or exposure to pro-inflammatory stimuli, such as interferon-gamma (IFNγ)." (PMID 38310187, 2024). "It has been reported that the ginsenosides Rg1 and Rf improve memory loss and cognitive dysfunction by regulating NF-κB, NLRP1, TLR3, and TLR4 signaling pathways, or interferon-gamma (IFN-γ) and active caspase-1 in an Alzheimer’s disease model." (PMID 38012459, 2024). "Microglia are readily activated by proinflammatory cytokines IFNγ and IL-17 under EAE and Alzheimer’s disease conditions." (PMID 33397973, 2021).
metastatic melanoma (59 papers, 2012 to 2025). A melanoma that has spread from its primary site to another anatomic site. "We report that expression of the IFNγ receptor β chain (IFNγR2) in CD8 T cells negatively correlates with clinical responsiveness to checkpoint blockade in metastatic melanoma patients, suggesting that the loss of sensitivity to IFNγ contributes to successful antitumor immunity." (PMID 36658158, 2023). "In our system, only DCs treated with the conditioned media of WM1617 and WM983B metastatic melanoma cell lines decreased the secretion of IFNγ by CD8+ T cells compared to its primary counterpart." (PMID 36194602, 2022). "In fact, the local production of IFNγ induced by ICKi, which are routinely used in the treatment of advanced/metastatic melanoma, leads to the modulation of proteasome composition, thus inducing the generation of antigenic peptides." (PMID 34638337, 2021). "Similarly, we have detected inhibited cytotoxic T cell activation in the presence of WM983B metastatic melanoma cell line-educated moDCs; in contrast, its primary counterpart induced the activation of IFNγ-producing CD8+ T cells." (PMID 36194602, 2022). "Of note, the local production of IFNγ within the tumor microenvironment by infiltrating T lymphocytes positively correlates with clinical outcomes to the ICKi therapy and cancer vaccination in tumors like metastatic melanoma." (PMID 34638337, 2021). "Immune checkpoint therapy regulates endothelial cell functions and reverses the immunosuppressive effects of VEGF in metastatic melanoma by decreasing intratumoral VEGF(R2) expression and consecutively activating CD8 + T cells via the IFNγ signalling pathway." (PMID 40591551, 2025). "Primary and metastatic melanoma cells express IDO1, and its expression is promoted by in vitro stimulation with interferon-gamma." (PMID 38791968, 2024). "These TILs came from a metastatic melanoma (MM33) and were characterized by their very high in vitro cytolytic capacity as measured by a viability assay and release of interferon gamma (IFNγ) in co-cultures of TILs and tumor cells." (PMID 28955032, 2017). "We collected PBMCs from 12 metastatic melanoma patients, stimulated them in vitro with the selected HLA-A *0201 epitopes and measured specific CD8 T-cell responses following restimulation either by IFNγ production (SF15-dec1 and GV17p) or tetramer staining (VS17p)." (PMID 40751736, 2025).